HOTAIR (HOX transcript antisense RNA)
Diseases named in the same sentence as HOTAIR in open-access papers (continued):
Sharing a sentence is not in itself a finding about the gene and the disease.
cervical carcinoma (continued). "In cervical cancer, HOTAIR plays an oncogenic role by promoting cell proliferation, migration, invasion, and autophagy, inhibiting cell apoptosis, stimulating angiogenesis, accelerating cell cycle progression, and inducing EMT." (PMID 36924407, 2023). "Prior study also revealed that genetic variation in the HOTAIR was correlated with HPV16 cervical cancer." (PMID 36438563, 2022). "Then, they performed further research to investigate the biological functions of HOTAIR in cervical cancer." (PMID 36685972, 2022). "Upregulation of HOTAIR reduced apoptosis and enhanced proliferation, migration and invasion and promoted cell cycle in cervical cancer cells." (PMID 36438563, 2022). "HOTAIR overexpression increased cell growth and invasion via modulation of Notch signaling pathway in cervical cancer." (PMID 36438563, 2022). "They found that circulating HOTAIR levels were significantly higher in cervical cancer patients and connected with a poor prognosis." (PMID 36685972, 2022). "Studies have fully proven that HOTAIR is highly expressed in cervical cancer tissues and cells, and is related to tumor proliferation and metastasis." (PMID 35692795, 2022). "Upregulation of HOTAIR regulated Notch-Wnt signaling pathway and EMT and caused induction of tumor growth in vitro and in vivo in cervical cancer." (PMID 36438563, 2022). "HOTAIR is significantly overexpressed in several human cancers, including cervical cancer, where circulating HOTAIR shows a higher level in patients compared to healthy controls, correlated with tumor aggressiveness." (PMID 35456025, 2022). "Compared with normal cervical epithelial cells (NCECs), the expression level of HOTAIR was significantly upregulated in cervical cancer cells such as HeLa and C33A cells." (PMID 36685972, 2022). "In these analysis results, some regulatory networks have been reported, such as the HOTAIR sponge miR-17-5p, which plays a tumor-promoting role in cervical cancer." (PMID 36115953, 2022). "Depletion of HOTAIR increased the expression of p21 and promoted the radio-sensitivity of C33A cervical cancer cells." (PMID 36438563, 2022). "The increased HOTAIR expression was connected with more enhanced clinical features and substantially shorter survival in patients with cervical cancer." (PMID 36144454, 2022). "For instance, HOTAIR has been correlated with cervical cancer recurrence as well as the functional role in ovarian, endometrial, and cervical cancers." (PMID 36232772, 2022). "This study found that HOTAIR expression was increased in cervical cancer tissues and correlated with age, FIGO stage, invasion and lymph node and tumor size." (PMID 36438563, 2022). "Further mechanistic studies showed that HOTAIR regulates the radiosensitivity of cervical cancer cells and is related to HIF-1α expression." (PMID 35692795, 2022). "For example, in cervical cancer, lncRNA HOTAIR enhances proliferation and suppresses apoptosis by binding to miR-214-3p." (PMID 35030969, 2022). "Another study revealed that HOTAIR upregulation stimulated cell viability, invasion, migration, and reduced apoptosis via modulation of HLA-G expression by sponging miR-148a in cervical cancer." (PMID 36438563, 2022). "They finally concluded that HOTAIR acts as an oncogene in cervical cancer and then cultured primary cervical cancer cells from 25 fresh cervical cancer tissues to investigate the relationship between HOTAIR and the response to RT." (PMID 36685972, 2022). "HOTAIR not only promotes the proliferation and invasion of cervical cancer cells, but is also related to the recurrence of cervical cancer." (PMID 35262965, 2022). "In vitro experiments showed that depletion of HOTAIR blocked proliferation, invasion and migration of cervical cancer cells." (PMID 36438563, 2022). "Propofol has been found to reduce tumor size and suppress cell proliferation as well as induce cell apoptosis via inhibition of HOTAIR and modulation of mTOR/p70S6K pathway in cervical cancer." (PMID 36438563, 2022).
cervical carcinoma (continued). "This work found that rs2366152C was highly represented in HPV positive cervical cancer patients with lower expression of HOTAIR and higher expression of miR-22." (PMID 36438563, 2022). "It has been previously reported that HOTAIR was downregulated in the HPV16-positive SiHa cervical carcinoma line but was overexpressed in HPV18-positive HeLa cells." (PMID 36366537, 2022). "HOTAIR, a long non-coding RNA, is involved in the tumorigenesis of cervical cancer and was found to bind with miR-29b." (PMID 36430305, 2022). "In this study, we found when HOTAIR was knocked down in HPV16 positive cervical cancer cells, the expression of β-catenin was significantly inhibited." (PMID 34320988, 2021). "HOTAIR was significantly overexpressed in cervical cancer stem cells, and knockdown of HOTAIR generated statistical downregulation of stemness markers." (PMID 34539782, 2021). "Similarity of migration and invasion suggested that HOTAIR should exert a positive effect on stemness acquisition of cervical cancer cells." (PMID 34539782, 2021). "We found that transfection with small interference RNA targeting HOTAIR resulted in a statistical increase of miR-203 compared with those normal control cells, indicating that miR-203 was negatively correlated with HOTAIR in cervical cancer cells." (PMID 34539782, 2021). "HOTAIR plays an important oncogenic role in cervical cancer, promoting the proliferation, migration, and invasion of cancer cells." (PMID 33540611, 2021). "HOTAIR via sponging miR-17-5p can promote proliferation, migration, and invasion of cervical cancer cells." (PMID 33540611, 2021). "Notability, these results were completely contrary to the function and effect of HOTAIR in cervical cancer cells." (PMID 34320988, 2021). "We supposed that HOTAIR was responsible for miR-214-3p down-regulation in HPV16 positive cervical cancer by serving as a competitive endogenous RNA through sponging mature miR-214-3p in cells." (PMID 34320988, 2021). "In cervical cancer, HOTAIR and MALAT1 were upregulated and MEG3 was downregulated within the cervicovaginal lavage in cervical cancer patients." (PMID 34067896, 2021). "Although studies have shown that Artesunate can inhibit the overexpression of HOTAIR and thereby reduce the metastasis of cervical cancer cells." (PMID 34482818, 2021). "Several reports have described that upregulation of HOTAIR stimulates the Wnt/β-catenin pathway in several types of cancer including lung, pancreatic, ovarian and cervical cancer; mainly in HeLa cells." (PMID 34778043, 2021). "The results suggest that the infection status of HPV16 played an important role in regulating expression of HOTAIR or miR-214-3p in cervical cancer cells." (PMID 34320988, 2021). "In this study, we detected the expression of HOTAIR and miR-214-3p in cervical cancer cells, conducted the target genes and pathway enrichment analysis with bioinformatics analysis." (PMID 34320988, 2021). "In cervical cancer cells, HOTAIR also promotes the expression of the human leukocyte antigen-G (HLA-G), a newly identified member of the non-classical MHC family, through inhibition of miR-148a expression." (PMID 33540611, 2021). "The role of HOTAIR in migration and invasion of cervical cancer cells was determined in vitro through both gain-of-function and loss-of-function approaches." (PMID 34539782, 2021). "The expression status of HPV16 E7 played an important role in regulating expression of HOTAIR or miR-214-3p in cervical cancer cells." (PMID 34320988, 2021). "For better investigate the function of HOTAIR and miR-214-3p in HPV16 positive cervical cancer, we knocked down HOTAIR and upregulated miR-214-3p in HPV16 positive cells, respectively." (PMID 34320988, 2021). "HOTAIR was statistically upregulated along with enrichment of cervical cancer stem cells, and knockdown of HOTAIR significantly downregulated the expressions of stemness markers." (PMID 34539782, 2021).
cervical carcinoma (continued). "TCGA database revealed that the cervical cancer tissues with the rs7958904 CC genotype had increased the expression of HOTAIR compared to those with GG genotype." (PMID 33028884, 2020). "Recent study has shown that lncRNA HOTAIR (OMIM# 611400) was heightened in cervical cancer tissues and correlated with poor prognosis of cervical cancer patients (Li, Wang, Yu, Dong, & Qiu, 2015)." (PMID 32329235, 2020). "HOTAIR was also reported to be highly expressed in cervical cancer tissues, but another study reported that HOTAIR levels were lower." (PMID 32326624, 2020). "In cervical cancers, HOTAIR overexpression is able to induce radio-resistance via inhibiting p21, and its knockdown, by upregulating p21, increases the radio-sensitivity of cervical cancer cells." (PMID 32397382, 2020). "For instance, HOTAIR is a lncRNA that plays a key role in several cancers such as breast, gastric, colorectal, and cervical cancers and the expression level of HOTAIR is a potential biomarker for diagnostic and therapeutic purposes." (PMID 30867411, 2019). "Compared with normal tissue, HOTAIR expression level increased 2.2 fold (p = 0.0045) in cervical cancer tissue, and HIF-1α expression was also upregulated in cervical cancer tissue." (PMID 30355300, 2018). "In the present study, we found that HOTAIR was greatly decreased in cervical tumor from mice and cervical cancer cells exposed to radiotherapy." (PMID 30355300, 2018). "Studies have demonstrated that the high expression of HOTAIR can be used as a predictor for poor prognosis of cervical cancer." (PMID 30518760, 2018). "In the current study, we found that HOTAIR overexpression induced the radioresistance through upregulating the expression of HIF-1α in cervical cancer cells." (PMID 30355300, 2018). "It is worth to note that several lncRNAs, such as GAS5 and HOTAIR show clinical values for the diagnosis and prognosis of cervical cancers." (PMID 29760583, 2018). "HOTAIR is highly expressed in cervical cancer tissues and cells, which is correlated with lymph node metastasis, survival rate and postoperative recurrence." (PMID 30518760, 2018). "Immunofluorescence analysis was used to analyze the expression of HOTAIR in cervical cancer tissues." (PMID 29391067, 2018). "At the same time, suppression of lncRNA HOTAIR can reduce the proliferation, migration and invasion of cervical cancer cells and decrease the expressions of some metastasis-associated proteins (VEGF and MMP-9) and EMT-related proteins." (PMID 30518760, 2018). "The study revealed that HOTAIR is elevated in cervical cancer tissues, where it correlated with more aggressive biological behaviors, such as late tumor stages, lymph node metastases, and deep cervical invasions." (PMID 28649178, 2017). "A recent study elucidated a role for HOTAIR in the development of cervical cancer by analyzing 218 pairs of cervical cancer and adjacent normal tissues." (PMID 28649178, 2017). "Both of these two studies focused on exploring a single lncRNA (H19 or HOTAIR) in relation to cervical cancer." (PMID 28977961, 2017). "In another study, we further explored the role of HOTAIR in the regulation of the radiosensitivity of cervical cancer." (PMID 28649178, 2017). "Recently, we have also found that HOTAIR plays a functional role in ovarian, endometrial, and cervical cancers." (PMID 28649178, 2017). "In the enrolling studies, PVT1 and HOTAIR were investigated in two or more articles, and with the increased expression of the two lncRNAs, the prognosis rate was poor in cervical cancer." (PMID 28977961, 2017). "The increased HOXD10 expression among the cervical cancer cases recorded in our previous report, correlated negatively with lncRNA HOTAIR expression." (PMID 28402266, 2017). "HOTAIR contributes to chemo-resistance of lung adenocarcinoma and cervical cancer via inhibiting p21 expression." (PMID 29212230, 2017).
cervical carcinoma (continued). "On the other hand, in our earlier report, we interpreted the increased HOXD10 expression in cervical cancer cases to be the result of E7-dependent inactivation of HOTAIR mediated gene silencing through PRC2-LSD1 complex." (PMID 28402266, 2017). "Univariate analysis revealed that disease-free survival and overall survival times were significantly shorter in cervical cancer patients with high HOTAIR expression (hazard ratio [HR] = 4.27, 4.68 and P = 0.039, 0.031, respectively)." (PMID 27323817, 2016). "In this study, we have found that HOTAIR expression was significantly inhibited in cervical cancer cells induced by ART." (PMID 27736969, 2016). "We investigated the functional role and clinical significance of circulating HOTAIR using serum from cervical cancer patients, cervical cancer cell lines, and mouse xenograft models." (PMID 27323817, 2016). "The present study demonstrated that HOTAIR expression was obviously decreased in cervical cancer cells treated with ART." (PMID 27736969, 2016). "HOTAIR expression was higher in cervical cancer tissues than that in corresponding normal tissues, and the high expression was associated with the TT genotype of rs920778." (PMID 27467165, 2016). "Compared with control patients, HOTAIR expression was significantly greater in the serum of cervical cancer patients (P < 0.001)." (PMID 27323817, 2016). "HOTAIR overexpression was positively correlated with cell migration and invasion in cervical cancer cell in vitro cultures, and with in vivo tumour growth in xenograft-bearing mice." (PMID 27323817, 2016). "Cell proliferation and invasion in vitro increased as a result of lentiviral-mediated HOTAIR overexpression in cervical cancer cell lines." (PMID 27323817, 2016). "We further analyzed HOTAIR expression levels in 3 cervical cancer cell lines and 91 pairs of cervical cancer tissues and the adjacent noncancerous tissues." (PMID 27467165, 2016). "HOTAIR overexpression partially abolished the anti-metastatic effect of ART on cervical cancer cells." (PMID 27736969, 2016). "In this meta-analysis, we found that HOTAIR expression was significantly higher in cervical cancer tissues than in normal tissues." (PMID 27897239, 2016). "In summary, in this meta-analysis investigating the role of HOTAIR in cervical cancer, we confirmed that abnormal expression of HOTAIR was closely related to cervical cancer development, metastasis, and invasion." (PMID 27897239, 2016). "The analysis showed that HOTAIR expression was significantly increased in cervical cancer compared with that in the normal control group." (PMID 27897239, 2016). "Similar results were also observed in 43 cervical cancer tissues from cervical cancer patients with the HOTAIR polymorphic rs920778 CT+TT genotypes." (PMID 27467165, 2016). "As shown in, high HOTAIR expression in cervical cancer was significant correlation with high TNM stage (II+III+IV) (P<0.05)." (PMID 27467165, 2016). "The function of HOTAIR in cervical cancer development, and its fundamental molecular mechanisms, are also unclear." (PMID 27323817, 2016). "Enhanced serum HOTAIR expression was positively correlated with clinicopathological parameters in in vitro and in vivo cervical cancer cells." (PMID 27323817, 2016). "We examined serum HOTAIR expression levels in cervical cancer patients and determined the relationships between HOTAIR expression and several clinicopathological factors, including survival." (PMID 27323817, 2016). "Here, we performed a meta-analysis to evaluate the expression levels and clinical significance of HOTAIR in cervical cancer tissue." (PMID 27897239, 2016). "We previously observed that HOTAIR transcription is upregulated by more than 30-fold in cervical cancer tissues by qRT-PCR." (PMID 27323817, 2016). "Evidence suggests that the long non-coding RNA (lncRNA), HOTAIR, is involved in cervical cancer pathogenesis." (PMID 27323817, 2016).
cervical carcinoma (continued). "A meta-analysis revealed that HOTAIR overexpression correlated with lymph node metastasis in many cancers including cervical cancer." (PMID 27736969, 2016). "Long non-coding RNAs (lncRNAs), HOTAIR has been reported to be upregulated in cervical cancer development and progression." (PMID 27467165, 2016). "In this study, the expression level of HOTAIR in cervical cancer was positively related to tumour size and lymph node metastasis." (PMID 27897239, 2016). "HOTAIR knockdown led to a decrease of proliferation, migration, and invasion in cervical cancer cells." (PMID 27736969, 2016). "The results indicate that aberrant expression of lncRNA HOTAIR was consistent with the previous report in cervical cancer." (PMID 27467165, 2016). "Consisted with previously published study on the biology of HOTAIR in cervical cancer, in our study, it is generally showed that HOTAIR played a critical role in cervical cancer." (PMID 27467165, 2016). "Our findings suggested that HOTAIR is one of the critical lncRNAs contributing to cervical cancer carcinogenesis and progression." (PMID 27323817, 2016). "Collectively, these results indicate that HOTAIR has an important role in the migratory and invasive phenotype of cervical cancer cells." (PMID 25405331, 2015). "Knockdown of HOTAIR reduced cell proliferation, migration, and invasion in cervical cancer cell lines." (PMID 25405331, 2015). "The expression of HOTAIR lncRNA was determined in cervical cancer tissues (n=111) and corresponding normal tissues (n=40) using qRT-PCR." (PMID 25405331, 2015). "In the present study, we examined the expression and the functional role of HOTAIR in cervical cancer." (PMID 25405331, 2015). "HOTAIR expression was determined in cervical cancer tissues (n=111) and corresponding normal tissues (n=40) by using real-time polymerase chain reaction, and its correlation with clinical parameters and prognosis were analyzed." (PMID 25405331, 2015). "Collectively, the dysregulation of the expression of EMT-related genes partially explains the involvement of HOTAIR in cervical cancer cell migration and invasion." (PMID 25405331, 2015). "Knockdown of HOTAIR expression decreased cell growth, migration and invasion in cervical cancer cells." (PMID 25405331, 2015). "Several studies reported that multiple lncRNAs were dysregulated in HCC and cervical cancer, such as HOTAIR and MEG3." (PMID 26147888, 2015). "In the present study, we determined the expression and clinical significance of HOTAIR in cervical cancer." (PMID 25405331, 2015). "In the present study, we showed that high HOTAIR expression was correlated with lymph node metastasis and recurrence in cervical cancer." (PMID 25405331, 2015). "For this, HOTAIR expression in SiHa, Caski and HeLa cervical cancer cell lines was first determined using qRT-PCR." (PMID 25405331, 2015). "To determine the effect of HOTAIR knockdown and overexpression in cervical cancer cell lines, we used the CCK-8 assay, wound healing migration and Matrigel invasion assay." (PMID 25405331, 2015). "In the present study, we found that downregulation of HOTAIR expression decreased cervical cancer cell proliferation, migration and invasion." (PMID 25405331, 2015). "HOTAIR is an lncRNA that plays a role as an oncogenic molecule in different cancer cells, such as breast, gastric, colorectal, and cervical cancer cells." (PMID 25859406, 2015). "Targeting HOTAIR or its downstream pathways may offer a promising strategy to overcome resistance and improve therapeutic responses in cervical cancer patients (reviewed in 90)." (PMID 41195272, 2025). "HOTAIR was shown to induce resistance of cervical cancer cell lines HeLa and Siha to cisplatin, docetaxel, and paclitaxel, which could be reversed by miR-29b upregulation." (PMID 39403602, 2024).